METTL8 (methyltransferase 8, tRNA N3-cytidine)
Description:
Mitochondrial S-adenosyl-L-methionine-dependent methyltransferase that mediates N(3)-methylcytidine modification of residue 32 of the tRNA anticodon loop of mitochondrial tRNA(Ser)(UCN) and tRNA(Thr). N(3)-methylcytidine methylation modification regulates mitochondrial translation efficiency and is required for activity of the respiratory chain. N(3)-methylcytidine methylation of mitochondrial tRNA(Ser)(UCN) requires the formation of N(6)- dimethylallyladenosine(37) (i6A37) by TRIT1 as prerequisite. May also mediate N(3)- methylcytidine modification of mRNAs. The existence of N(3)-methylcytidine modification on mRNAs is however unclear, and additional evidences are required to confirm the role of the N(3)- methylcytidine-specific mRNA methyltransferase activity of METTL8 in vivo.
Synonyms: FLJ13984; TIP
Tractability: PROTAC: UniProt records ubiquitination sites on it; ubiquitination databases record sites on it.
Gene: Protein-coding gene on chromosome 2 (171,315,746 to 171,434,802, reverse strand). Ensembl gene ENSG00000123600.
Subcellular location: Mitochondrion
Subcellular location (Human Protein Atlas): Cytosol
Gene Ontology:
Molecular function: mRNA methyltransferase activity; tRNA (cytidine-3-)-methyltransferase activity; RNA methyltransferase activity; S-adenosylmethionine-dependent methyltransferase activity
Biological process: mitochondrial tRNA modification; mRNA metabolic process; positive regulation of mitochondrial translation; tRNA C3-cytosine methylation
Cellular component: cytoplasm; mitochondrial matrix; mitochondrion; nucleus
Genetic constraint (gnomAD): Loss-of-function variants: 15 observed, 26.98 expected, observed/expected ratio (o/e) 0.56, 90% interval 0.37 to 0.86. The upper end of that interval is the gene's LOEUF score, 0.86, which puts it in group 3 of 6, group 1 being the genes least tolerant of losing a copy. Missense variants: 307 observed, 334.34 expected, observed/expected ratio (o/e) 0.92, 90% interval 0.84 to 1.01. Synonymous variants: 96 observed, 111.95 expected, observed/expected ratio (o/e) 0.86, 90% interval 0.73 to 1.02.
Homologues: Orthologues: macaque METTL8 (94% identical), chimpanzee METTL8 (84% identical), dog METTL8 (84% identical), pig METTL8 (84% identical), rabbit METTL8 (80% identical), guinea pig METTL8 (77% identical), mouse Mettl8 (72% identical), rat Mettl8 (71% identical), zebrafish mettl8 (48% identical). Paralogues in human: METTL2A (48% identical), METTL2B (47% identical), METTL6 (28% identical).